PON1 (paraoxonase 1)
Diseases named in the same sentence as PON1 in open-access papers (continued):
Sharing a sentence is not in itself a finding about the gene and the disease.
atrial fibrillation (1 paper, 2024). A disorder characterized by an electrocardiographic finding of a supraventricular arrhythmia characterized by the replacement of consistent P waves by rapid oscillations or fibrillatory waves that vary in size, shape and timing and are accompanied by an irregular ventricular response. "The explanation for this finding can be that atrial fibrillation’s risk factors are the same that lead to lower PON1 levels." (PMID 38474211, 2024). "Interestingly, a newer study has found that PON1 and its arylesterase activity were diminished in patients with atrial fibrillation." (PMID 38474211, 2024). "Still, atrial fibrillation is responsible for the changes in PON1, but not for its activity." (PMID 38474211, 2024).
babesiosis (1 paper, 2018). Babesiosis refers to a condition caused by microscopic parasites that infect the red blood cells. "Paraoxonase 1 (PON-1) has been observed to inhibit this process decreasing endothelial MCP-1 secretion and previous studies have indicated a decrease in PON-1 concentration in acute babesiosis." (PMID 29304171, 2018).
Cachexia (1 paper, 2020). Severe weight loss, wasting of muscle, loss of appetite, and general debility related to a chronic disease. "This contrast in the loss of plasma PON1 in cachectic males, but not in noncachectic females may suggest maintenance of PON1 as a protective mechanism from cachexia in the female mouse." (PMID 33063952, 2020). "However, effective approaches to ameliorate such oxidative stress in cachexia are not known, thus PON1 may present a novel target of interest." (PMID 33063952, 2020).
cataract (1 paper, 2019). Partial or complete opacity of the crystalline lens of one or both eyes that decreases visual acuity and eventually results in blindness. "Low PON1 activity has also been found to be associated with the pathogenesis of cataracts." (PMID 30857240, 2019). "In addition, loss of PON1 activity is associated with the pathogenesis of both cataracts and AMD." (PMID 30857240, 2019).
cerebral palsy (1 paper, 2022). A group of disorders affecting the development of movement and posture, often accompanied by disturbances of sensation, perception, cognition, and behavior. "We detected low PON-1 activity and increased HDL level in children with cerebral palsy in our study group, which may be a risk factor in advancing age." (PMID 36326319, 2022). "Therefore, determination of PON-1 activity may play a role in the early diagnosis of cerebral palsy and follow-up in long term may give information about the tendency of cardiovascular diseases." (PMID 36326319, 2022).
cervical cancer (1 paper, 2024). A primary or metastatic malignant neoplasm involving the cervix. "This research is the only one where the PON1 paraoxonase and arylesterase activity and the PON1 concentration were investigated in patients with cervical cancer, and where its decreased activity together with its lowered concentration was found." (PMID 38125616, 2024). "However, limited research data are available on PON1 paraoxonase and arylesterase activity as well as PON1 concentration in patients with cervical cancer." (PMID 38125616, 2024). "Our results indicate that the reduction of the PON1 arylesterase activity is present in the premalignant phase of the disease and could be one of the factors which can lead to the development of cervical cancer in future." (PMID 38125616, 2024).
cervical intraepithelial neoplasia (1 paper, 2024). "The aim of the study was to investigate the differences in PON1 activity and oxidation stress parameters between patients with cervical intraepithelial neoplasia (CIN) and healthy controls." (PMID 38125616, 2024).
Chronic constipation (1 paper, 2023). Constipation for longer than three months with fewer than 3 bowel movements per week, straining, lumpy or hard stools, and a sensation of anorectal obstruction or incomplete defecation. "Pon1 was found to have been significantly related to chronic constipation in a cross-sectional study." (PMID 36902274, 2023).
chronic hepatitis C (1 paper, 2021). "Individuals with chronic hepatitis C compared with healthy individuals showed a higher frequency of the arginine-containing PON-1 (RR192 isoform) associated with the PON1 rs662 GG genotype." (PMID 34445971, 2021).
chronic pancreatitis (1 paper, 2020). A chronic inflammatory process causing damage and fibrosis of the pancreatic parenchyma. "Since genetic variations may result in altered activity of PON1, Verlaan et al42investigatedPON1variants as a modifying factor of chronic pancreatitis." (PMID 32939514, 2020).
Constipation (1 paper, 2023). Infrequent or difficult evacuation of feces. "The relative mRNA expression of the core targets (Alb and Pon1) from the PPI network and other constipation-related targets (Cnr1, Nos, Ache and Grp) were further analyzed by qPCR." (PMID 36902274, 2023). "As a result, we found that DEGs (DHC vs. Lop) and constipation targets shared seven overlapping targets, and the PPI network of overlapping targets further revealed that Alb and Pon1 were the two main targets in the PPI network." (PMID 36902274, 2023).
convulsion (1 paper, 2023). A rapid and repeated body muscle contract that results in an uncontrolled shaking of the body. "Classical studies have shown that treatments with doses of chlorpyrifos oxone that do not affect Pon1+/+ mice induce convulsions and death in Pon1−/− animals." (PMID 37175471, 2023).
delirium (1 paper, 2023). A disorder characterized by confusion; inattentiveness; disorientation; illusions; hallucinations; agitation; and in some instances autonomic nervous system overactivity. "Therefore, the delirium-specific increase in PON1 in SAD-patients due to polypharmacy cannot be excluded." (PMID 37958765, 2023).
Encephalopathy (1 paper, 2025). Encephalopathy is a term that means brain disease, damage, or malfunction. "Notably, the inclusion of covariates did not reduce the prognostic significance of the PON1 genotype concerning the development of functional impairment in patients with this type of encephalopathy." (PMID 40283626, 2025).
Fabry disease (1 paper, 2021). Fabry disease (FD) is a progressive, inherited, multisystemic lysosomal storage disease characterized by specific neurological, cutaneous, renal, cardiovascular, cochleo-vestibular and cerebrovascular manifestations. "In a theoretical example, if we were interested in the expression of PON1 in Fabry’s disease, we could perform qPCR to assess the difference between patients with Fabry’s disease and healthy controls." (PMID 34882702, 2021). "However, if we were to choose GAPDH (Fabry vs Normal FC 0.49) as RG we would have to conclude that PON1 is overexpressed in Fabry’s disease, as the GAPDH gene itself is significantly decreased in patients with Fabry disease." (PMID 34882702, 2021). "YWHAZ (Fabry vs Normal FC: 1.05) is stable in Fabry’s disease, no bias is introduced, and the results show that PON1 is not differentially expressed." (PMID 34882702, 2021). "In our data PON1 was not affected in Fabry’s disease (Fabry vs Normal FC: 0.97)." (PMID 34882702, 2021).
Glucose intolerance (1 paper, 2016). Glucose intolerance (GI) can be defined as dysglycemia that comprises both prediabetes and diabetes. "Deficiency of PON1 leads to glucose intolerance as well as glycogen accumulation in muscle, while forced overexpression of PON1 in muscle cells enhances GLUT4 expression." (PMID 27656402, 2016).
Gulf War Syndrome (1 paper, 2019). "PON1 genes were associated with Gulf War Syndrome whose complaints of olfactory dysfunction are extensively shared with those of MCS." (PMID 31881664, 2019).
gynecological cancers (1 paper, 2022). "Nevertheless, there are still few data from the literature describing the prognostic significance of PON1 in cancers, especially gynecological cancers." (PMID 36290747, 2022).
hemochromatosis (1 paper, 2024). A disorder of iron metabolism characterized by a triad of HEMOSIDEROSIS; LIVER CIRRHOSIS; and DIABETES MELLITUS. "Patients suffering from hemochromatosis, which manifests itself with iron overload, have significantly lower PON1 activity, and its decrease is inversely correlated with ferritin level." (PMID 39684839, 2024). "Moreover, there is a higher expression of PON1 in the liver of hemochromatosis patients, especially in the most inflamed areas of the liver tissue." (PMID 39684839, 2024).
hemophilia B (1 paper, 2020). Hemophilia B is a form of hemophilia characterized by spontaneous or prolonged hemorrhages due to factor IX deficiency. "INS regulates vascularization; APOH, F2, and ICAM regulate platelet activation and adhesion; AGT regulates blood vessel contraction; TNF and CCL2 regulate blood chemokine in circulation; F9 regulates onset Hemophilia B, and PON1 inhibits onset cardiovascular disease." (PMID 32753925, 2020).
hyperandrogenism (1 paper, 2023). Excessive secretion of androgens from the adrenal glands or gonads. "It has been shown that there is an inverse correlation between Pon1 and hyperandrogenism due to PCOS37." (PMID 36653487, 2023).
hyperlipemia (1 paper, 2019). "In particular, induction of hyperlipemia in rats fed a hyperlipemic rich diet for 90 consecutive days was accompanied by a significant increase of ACAT and CETP, this effect being associated with a significant reduction of LCAT and PON1 compared to normolipemic animals." (PMID 31101130, 2019). "The effect of BPF in counteracting alteration of the lipemic serum and glycemic profile induced by diet-related hyperlipemia was accompanied by significant improvement of Lipid Transport Protein System as detected by measurements of ACAT, LCAT, CETP and PON1." (PMID 31101130, 2019).
Hyperoxaluria (1 paper, 2018). Increased excretion of oxalates in the urine. "The ability of quercetin to promote serum PON1 also provided an efficient antioxidant effect on hyperoxaluria-induced rats." (PMID 29518971, 2018).
ischemic colitis (1 paper, 2012). Inflammation of the colon due to colonic ischemia resulting from alterations in systemic circulation or local vasculature. "In our study, there was a significant decrease in both serum and tissue PON1 activity in ischemic colitis group." (PMID 23197980, 2012). "In the present study, we investigated the possible changes in PON1 activity and lipid profile with particular emphasis on the oxidative stress in an experimental ischemic colitis model." (PMID 23197980, 2012). "There was a significant decrease in both serum and tissue PON1 activity in ischemic colitis group (P < 0.01, for each)." (PMID 23197980, 2012). "PON1 and arylesterase play an important role in the pathophysiology of ischemic colitis." (PMID 23197980, 2012). "Although the role of lipid peroxidation in mesenteric ischemia has been reported, there is no study on the changes of PON1 with particular emphasis on the lipid profile and oxidative stress in ischemic colitis." (PMID 23197980, 2012). "In the present study, since PON1 is known as an antioxidant enzyme that inhibits the oxidative modification of LDL and oxidative stress plays a role in the pathogenesis of mesenteric ischemia, we investigated the changes in PON1 activity and lipid profile in an experimental ischemic colitis model." (PMID 23197980, 2012).
Jaundice (1 paper, 2024). Yellow pigmentation of the skin due to bilirubin, which in turn is the result of increased bilirubin concentration in the bloodstream. "The dogs with jaundice had lower PON-1 levels, while those with fatty blood had higher levels." (PMID 39409835, 2024).
liver failure (1 paper, 2024). A liver disease characterized by the liver losing or has lost all of its function. "Nevertheless, the results of this study suggest that a very low level of PON-1 activity may be associated with liver failure in dogs." (PMID 39409835, 2024). "The dogs with a suspicion of liver failure based on laboratory findings had lower PON-1 activity compared to both the controls and the dogs with suspected liver injury." (PMID 39409835, 2024). "The dogs in the suspected liver failure group had significantly lower PON-1 levels compared to those in the other groups." (PMID 39409835, 2024). "The use of PON-1 as a biomarker for liver failure goes beyond the aim of the present study." (PMID 39409835, 2024).
lupus nephritis (1 paper, 2011). Glomerulonephritis in the context of systemic lupus erythematosus. "Our group previously reported modest associations of three PON1 promoter SNPs with lupus nephritis in Caucasian SLE patients." (PMID 21223581, 2011). "Our previous reports with SLE datasets have identified low PON activity as an independent risk factor for SLE and our analysis of PON1 and PON3 SNPs revealed some modest associations with lupus nephritis." (PMID 21223581, 2011).
melanoma (1 paper, 2021). A malignant, usually aggressive tumor composed of atypical, neoplastic melanocytes. "By proteomics we identified five proteins in plasma CD81sEV that were differentially expressed between HD and stage II (APOA5, PON1, PON3 and CD14) and between HD and stage III–IV, advanced stage melanoma, (RAP1B)." (PMID 34439311, 2021). "To explore whether the identified proteins, APOA5, PON1, PON3, CD14 and RAP1B, could be of any clinical relevance, we evaluated their expression in silico in relation to the available clinical information in the TCGA dataset of primary melanoma samples (PM, n = 80)." (PMID 34439311, 2021).
metastatic cancer (1 paper, 2025). A carcinoma which has spread from the original site of growth to another anatomic site. "According to another study, metastatic cancer patients who received chemotherapy had SOS genes including NQO1 and PON1 as notable predictors of their prognosis." (PMID 39958338, 2025).
metastatic melanoma (1 paper, 2021). A melanoma that has spread from its primary site to another anatomic site. "To explore the clinical relevance of APOA5 and PON1 as well, we selected a dataset containing RNA-seq data from circulating plasma-derived EV of metastatic melanoma patients." (PMID 34439311, 2021).
migraine (1 paper, 2022). "In a subsequent investigation, biochemical assays were used to analyse PON1 enzyme activity levels in a Turkish population of 104 migraine patients and 86 healthy participants to determine the risk of acquiring migraine." (PMID 35627115, 2022). "The PON1 serum activity has shown a significant drop in migraine patients." (PMID 35627115, 2022). "Interesting overlapping candidate genes for migraine and glucose-related traits are MTHFR, INSR, TNF, ESR1, NOS3, and PON1." (PMID 35627115, 2022).
Miscarriage (1 paper, 2021). A pregnancy that ends at a stage in which the fetus is incapable of surviving on its own, defined as the spontaneous loss of a fetus before the 22th week of pregnancy. "This study suggests an effect of genetic maternal PON1 polymorphisms on miscarriage and provides additional evidence that combines with the growing information about the ways in which certain PON1 genotypes can affect the development of the fetus in utero." (PMID 34822663, 2021).
mitral valve disease (1 paper, 2023). "In order to identify the association of Paraoxonase-1 and N-terminal-prohormone-B-type natriuretic peptide with selected clinico-pathologic and echocardiographic parameters in mitral valve disease, 80 dogs in various clinical stages were enrolled." (PMID 36669034, 2023).
myocardial disease (1 paper, 2022). "Taken together, the current study suggests that diminished levels of PON-1 promotes a pro-inflammatory and pro-fibrotic environment in the myocardium that leads to myocardial disease at the molecular, structural, and functional level." (PMID 36140402, 2022).
Myocardial fibrosis (1 paper, 2025). "The stepwise decline in TETRA may stem from impaired fibrinolysis or increased myocardial fibrosis, as suggested by its myocardial expression, while PON1’s reduction likely reflects heightened oxidative stress overwhelming its antioxidant capacity." (PMID 40422267, 2025).
Neonatal sepsis (1 paper, 2019). Systemic inflammatory response to infection in newborn babies. "Nonetheless, all studies concerning PON1 clearly indicate a significant drop in PON1 activity in adult as well as pediatric and neonatal sepsis." (PMID 30886652, 2019).
nephritis (1 paper, 2011). Inflammation of renal tissue. "Our pairwise LD analysis of the nephritis-associated three PON1 promoter SNPs (rs705379, rs705381 and rs854573) and three PON2 SNPs did not reveal high correlations between these SNPs (data not shown)." (PMID 21223581, 2011).
neutropenia (1 paper, 2016). A decrease in the number of neutrophils found in the blood. "According to our literature search, this is perhaps the first study evaluating the relationship between neutropenia/GCS-F and MDA, PON1 and ARE activities." (PMID 27182229, 2016). "In this study, MDA levels increased and antioxidant enzymes PON1 and ARE levels (along with HDL levels) decreased after the resolution of neutropenia secondary to chemotherapy." (PMID 27182229, 2016). "In our study, PON1, HDL, and LDH levels during the period of active neutropenia were statistically significantly higher than these levels were after resolution of neutropenia (P<0.05); MDA and ALP levels were statistically significantly lower during the period of active neutropenia (P<0.05)." (PMID 27182229, 2016).
osteonecrosis (1 paper, 2022). A none disease characterized by death of bone tissue due to a lack of blood supply. "However, another case-control study found that the carriers of the AA genotype of rs662 in PON1 were more susceptible to osteonecrosis of the femoral head than GG genotype carriers (OR = 2.53, 95% CI: 1.05 to 6.07)." (PMID 35646794, 2022).
pervasive developmental disorder (1 paper, 2022). A category of developmental disorders characterized by impaired communication and socialization skills. "Similar to our study, prior studies found no modification of associations of prenatal urinary DAPs with SRS scores and nonverbal IQ, MDI, PDI, and pervasive developmental disorder (PDD) scale scores by genetic variation in PON1." (PMID 35805806, 2022).
pneumonia (1 paper, 2022). An acute, acute and chronic, or chronic inflammation focally or diffusely affecting the lung parenchyma, caused by an infection in one or both of the lungs (by bacteria, viruses, fungi, or mycoplasma.). "Compared to patients with mild and moderate pneumonia, severely ill patients had higher CRP and MDA but lower plasma prooxidants TOS and O2− and antioxidants TAS, SOD, and PON1 levels." (PMID 36420478, 2022). "Compared to patients with mild and moderate pneumonia, severely ill patients had higher oxidised low-density lipoprotein (oxLDL) and malondialdehyde levels and lower high-density lipoprotein cholesterol (HDL-C) concentrations and paraoxonase 1 activity." (PMID 36420478, 2022).
postmenopausal osteoporosis (1 paper, 2024). Metabolic disorder associated with fractures of the femoral neck, vertebrae, and distal forearm. "Multiple studies have demonstrated that PON1 may be an important gene in the pathogenesis of postmenopausal osteoporosis." (PMID 38099525, 2024).
prediabetes (1 paper, 2023). "However, based on the results of the current study, compared with healthy counterparts, participants with prediabetes had higher levels of prooxidants (i.e., AOPP, TOS, PROOX score, and OXY score) and lower levels of antioxidants (i.e., PON1, and TAS)." (PMID 37814622, 2023).
Protein-losing enteropathy (1 paper, 2024). Abnormal loss of protein from the digestive tract related to excessive leakage of plasma proteins into the lumen of the gastrointestinal tract. "Since lipoproteins, C-reactive protein and paraoxonase-1 take part in inflammation, investigating their changes in dogs with protein-losing enteropathy secondary to chronic inflammatory enteropathy (iPLE) is crucial." (PMID 39518842, 2024).